ECM1 (extracellular matrix protein 1)
Diseases named in the same sentence as ECM1 in open-access papers (continued):
Sharing a sentence is not in itself a finding about the gene and the disease.
breast carcinoma (continued). "A detailed study with a larger cohort is necessary to establish ECM1 and ANXA1 in the uEVs as potential biomarkers for breast cancer before starting clinical application." (PMID 39040439, 2024). "In breast cancer, non-invasive detection through urinary biomarkers, such as MMP9, NGAL, CD63, ECM1, MAST4, and Filaggrin, offers insights into disease progression." (PMID 38250812, 2023). "Consistent with clinical samples, the short-term estrogen deprivation induced ECM1 expression in CAMA1, MDA-MB-361, and T47D cells, all of which are classified as ER+ breast cancer cell lines." (PMID 35784388, 2022). "The expression of ECM1 is much higher in a variety of tumor tissues, such as ovarian cancer, CRC, breast cancer, gastric cancer, etc., when compared with normal tissues." (PMID 36408224, 2022). "The analyses revealed that ECM1 is highly expressed in HER2-enriched and luminal subtypes compared to basal-like and normal-like subtypes in TCGA breast cancers." (PMID 35784388, 2022). "Preliminary validation of 3 potential markers (ECM1, MAST4 and filaggrin) identified was performed in breast cancer cell lines by Western blotting." (PMID 26544852, 2015). "Our previous study found that both ECM1 and vascular endothelial growth factor-C (VEGF-C) have a synergistic effect on lymphangiogenesis, so as to facilitate lymphatic metastasis of breast cancer." (PMID 24779890, 2014). "Our data demonstrate that both ECM1 and VEGF-C mRNA and protein were overexpressed in breast cancer specimens compared to their corresponding normal counterparts and axillary lymph nodes." (PMID 22284579, 2012). "The present study was designed to investigate the expression pattern of ECM1 and VEGF-C in tumor specimens, their peritumoral normal counterparts and axillary lymph nodes from 41 breast cancer patients." (PMID 22284579, 2012). "We used real-time RT-PCR to determine the mean relative expression levels of ECM1 mRNA and VEGF-C mRNA in breast cancer specimens, normal epithelia and lymph nodes from the patients." (PMID 22284579, 2012). "This suggests that ECM1 and ANXA1 in uEVs could be potential biomarkers for early diagnosis of breast cancer." (PMID 39040439, 2024). "Furthermore, we also evaluated the changes of ECM1 and ANXA1 levels in the uEVs from breast cancer patients before and after surgery using CLIA." (PMID 39040439, 2024). "In addition, the protein levels of ECM1 and ANXA1 in the uEVs of MMTV-PyMT transgenic mice were observed to increase progressively with the progression of breast cancer." (PMID 39040439, 2024). "Survival analyses using the Kaplan-Meier plotter showed that the level of ECM1 expression is not prognostic in the whole group of ER+ breast cancer patients." (PMID 35784388, 2022). "Extracellular matrix protein 1 (ECM1) is a glycoprotein secreted in the extracellular matrix and overexpressed in several cancer types, including breast cancer." (PMID 35784388, 2022). "We confirmed the feasibility of ECM1 as a universal TAA, identified the predominant HLA-A2.1-restricted epitopes derived from ECM1 (LA and YL), and verified their immunogenicity to induce DCs to elicit CD8+ T cells and potent cytotoxicity against breast cancer in vitro and in vivo." (PMID 33910591, 2021). "There is also evidence that ECM1 potentiates the phosphorylation of epidermal growth factor receptor (EGFR) and extracellular signal-regulated kinase through physical interaction with EGFR and activation of EGFR signaling in breast cancer development." (PMID 32292720, 2020). "Indeed, we found that high levels of ECM1 in serum were directly and inversely related to overall survival in HER2-positive breast cancer patients (right)." (PMID 25499743, 2014). "ECM1 and VEGF-C may have a synergistic effect on lymphangiogenesis to facilitate the lymphatic metastasis of breast cancer." (PMID 22284579, 2012).
breast carcinoma (continued). "We conclude, therefore, that ECM1 and VEGF-C may have a synergistic effect on lymphangiogenesis to facilitate lymphatic metastasis of breast cancer." (PMID 22284579, 2012). "A previous study demonstrated that breast cancers with lymph node metastasis were more likely to be ECM1-positive (10/13, 76.9%) than those without metastasis (3/9, 33.3%)." (PMID 22284579, 2012). "The aim of this study was to investigate whether correlations exist between ECM1 and VEGF-C in human breast cancer, lymphangiogenesis, and the clinicopathological characteristics of the disease." (PMID 22284579, 2012). "Both ECM1 and VEGF-C were overexpressed in breast cancer tissue samples." (PMID 22284579, 2012). "Furthermore, ROC curve analysis demonstrated that the protein levels of ECM1 and ANXA1 in uEVs could effectively differentiate between breast cancer patients and healthy controls or patients with benign breast nodules." (PMID 39040439, 2024). "It is not possible to speculate whether ECM1 and ANXA1 in the uEVs are associated with the survival and cure rate of breast cancer." (PMID 39040439, 2024). "Finally, we examined the rate of ECM1 CNA in each PAM50 subtype of TCGA and MEABRIC breast cancers." (PMID 35784388, 2022). "However, the role of ECM1 with endocrine resistance in estrogen receptor-positive (ER+) breast cancers has not been elucidated yet." (PMID 35784388, 2022). "However, the role of ECM1 in ER+ breast cancers has not been elucidated." (PMID 35784388, 2022). "Meanwhile, LA/DC-CTL could exert significant cytotoxicity against HLA-A2.1+/ECM1+ breast cancer cell lines (MDA-MB-231 and BT-549), while no notable cytotoxicity on HLA-A2.1+/ECM1− breast epithelial cell line MCF-10A or HLA-A2.1−/ECM1+ breast cancer cell line MCF-7 was detected." (PMID 33910591, 2021). "Western blot analysis revealed that ECM1 and ANXA1 were highly expressed in the uEVs of breast cancer patients, but not in healthy controls or patients with benign nodules." (PMID 39040439, 2024). "The protein levels of ECM1 and ANXA1 in the uEVs of breast cancer patients with and without LVI were also compared." (PMID 39040439, 2024).
lipoid proteinosis (19 papers, 2005 to 2025). Lipoid proteinosis (LP) is a rare genodermatosis characterized clinically by mucocutaneous lesions, hoarseness developing in early childhood and, at times, neurological complications. "The discovery in 2002 that mutations in the ECM1 gene cause lipoid proteinosis significantly advanced our understanding of ECM1’s role in human skin physiology and pathology." (PMID 40362551, 2025). "Mutations in the ECM1 gene cause lipoid proteinosis, a rare condition characterized by an abnormal skin thickening, suggesting that this protein is important for skin adhesion, epidermal differentiation, and wound healing." (PMID 36482174, 2022). "More critically, loss-of-function mutations in the extracellular matrix protein 1 (ECM1) gene were demonstrated in an autosomal recessive genodermatosis referred to as lipoid proteinosis (LiP), a counterpart disease that is a similar skin pathology to LS." (PMID 36553077, 2022). "Loss-of-function mutation studies in ECM1 gene in lipoid proteinosis, an autosomal recessive genodermatosis that shows comparable clinical and histopathological features to those of LS, implicates ECM1 as a strong putative autoantigen in LS autoimmunity." (PMID 34440154, 2021). "Extracellular matrix protein 1 (ECM1) has been associated with lipoid proteinosis in which brain damage develops over time and is associated with the development of cognitive disabilities and epileptic seizures." (PMID 32671069, 2020). "This study identifies a novel nonsense mutation in exon 9 of the extracellular matrix protein 1 gene associated with lipoid proteinosis, contributing to recent advances in our understanding of the molecular genetics underlying this disease." (PMID 31205714, 2019). "Lipoid proteinosis is a rare autosomal recessive genodermatosis that is caused by loss-of-function mutations in the extracellular matrix protein 1 gene." (PMID 31205714, 2019). "It is important to identify the mutations in the extracellular matrix protein 1 gene that are associated with lipoid proteinosis and how these affect protein function." (PMID 31205714, 2019). "Lipoid proteinosis (LP) is known to be resulted from mutations of the extracellular matrix protein 1 gene (ECM1)." (PMID 24708644, 2014). "The loss of function mutations in Ecm1 in Lipoid proteinosis is thought affect its function in epidermal differentiation and basement membrane formation." (PMID 24391906, 2013). "Another, apparently restrictive, regulator of BM assembly “extracellular matrix protein 1”/ECM1 came across when analyzing skin biopsies of lipoid proteinosis (LP) patients with mutations in the ECM1 gene." (PMID 23586018, 2013). "Our studies identified a number of known RA-targets and several novel RA-regulated genes including Extracellular matrix protein 1 (hereafter Ecm1), a gene that when mutated in humans causes lipoid proteinosis and ulcerative colitis." (PMID 24391906, 2013). "Forty six mutations in the ECM1 gene have been described so far in unrelated patients affected with lipoid proteinosis." (PMID 21791056, 2011). "In this study we report a novel nonsense mutation in a consanguineous Pakistani family affected with lipoid proteinosis; and an update of ECM1 gene mutation data base." (PMID 21791056, 2011). "We report the neurologic and neuroradiologic characteristics and ECM1 gene mutations of seven individuals with lipoid proteinosis (LP) from three unrelated consanguineous families." (PMID 21349189, 2011). "Although lipoid proteinosis is confirmed genetically via ECM1 mutation analysis, CNS imaging may have a potential role in assessing disease extent and symptom correlation." (PMID 40727897, 2025). "Mutation of ECM1 may lead to various genetic diseases such as lipoid proteinosis and autosomal recessive genodermatosis." (PMID 36299684, 2022).
lipoid proteinosis (continued). "Lipoid proteinosis is a rare autosomal recessive disease characterized by cutaneous and mucosal lesions and hoarseness appearing in early childhood that is caused by homozygous or compound heterozygous mutations in the ECM1 gene located on chromosome 1q21." (PMID 21791056, 2011). "Homozygous loss-of-function mutations in the human ECM1 gene were recently identified by linkage analysis as the causative mutations behind Lipoid Proteinosis, a rare autosomal recessive disorder characterized by hyaline deposition in the skin, mucosae and viscera." (PMID 15642117, 2005). "Lipoid proteinosis is a rare autosomal recessive disease, characterized by hyaline deposits of PAS-positive material in tissues due to mutations in the ECM1 gene." (PMID 34544637, 2021). "The finding of a novel mutation in Pakistani family extends the body of evidence that supports the importance of ECM1 gene for the development of lipoid proteinosis." (PMID 21791056, 2011). "The study extends the body of evidence that supports the role of ECM1 gene in the development of lipoid proteinosis." (PMID 21791056, 2011). "Lipoid proteinosis (LP; MIM 247100) is a rare autosomal recessive disease characterized by cutaneous and mucosal lesions and hoarseness appearing in early childhood that is caused by homozygous or compound heterozygous mutations in the ECM1 gene located on chromosome 1q21." (PMID 21349189, 2011).
liver fibrosis (14 papers, 2019 to 2026). "The latency of deposited L-TGF-β is controlled by ECM1 in the healthy liver given that germline deletion of the ECM1 gene causes spontaneous liver fibrosis with hyperactivation of the TGF-β signaling in mice aged 8 to 12 weeks." (PMID 40350059, 2026). "Our study aimed to investigate the relationship between extracellular matrix 1 (ECM1) gene polymorphism and progression of liver fibrosis in the Chinese population." (PMID 36299684, 2022). "Our study might aid in understanding the effects of ECM1 gene polymorphism on the initiation and progression of liver fibrosis and on the occurrence of HCC." (PMID 36299684, 2022). "A recent study showed that ECM1 knockout (KO) leads to LTGF-β1 activation, causing hepatic fibrosis and rapid mortality." (PMID 40260391, 2025). "The current study confirm that ECM1 produced by hepatocytes inhibits TGFβ activation to prevent liver fibrosis in mice." (PMID 36211821, 2022). "The amount of ECM1 produced by hepatocytes is reduced when liver fibrosis occurs, while exogenous ECM1 supplementation can reverse hepatofibrosis by blocking HSC activation." (PMID 35136027, 2022). "We therefore conducted this large case-control study to evaluate the effects of ECM1 on the progression of liver fibrosis in vivo." (PMID 36299684, 2022). "Our lab reported that the extracellular matrix protein 1 (ECM1) plays a protective role in the development of liver fibrosis by keeping TGF-b in an inactive form via interaction with Integrin aV." (PMID 36293428, 2022). "Only PRG4 and ECM-1 demonstrated protection from steatosis and inflammation in high fat diet mouse models, and an inversed correlation with severity of liver fibrosis, respectively." (PMID 33262757, 2020). "When the liver is in a pathological state, the function of hepatocytes is damaged, leading to decreased ECM1 protein production by hepatocytes, subsequently promoting the occurrence and development of liver fibrosis." (PMID 32311840, 2020). "Ecm1-KO mice spontaneously developed severe liver fibrosis with tremendous TGF-β/Smad3 and subsequent HSC activation." (PMID 31718044, 2019). "The notion that ECM1 upregulation protects against liver fibrosis is further supported by the demonstration that genetically-induced overexpression of ECM1 in hair follicle-derived mesenchymal stem cells (HF-MSCs) improved their therapeutic potential for targeting cirrhosis." (PMID 40260391, 2025). "Conversely, in the liver, ECM1 knockout induces spontaneous hepatic fibrosis." (PMID 39910700, 2025). "In addition to these, we have identified ECM1 gene which is important for wound healing, tissue regeneration, and in disease progressions such as cancer and liver fibrosis." (PMID 35715992, 2023). "The therapeutic efficacy of ectopic ECM1 expression in the chronic CCl4 liver fibrosis mouse model was tested, and the results indicated that ECM1 was successfully expressed in the liver upon AAV8 infection and partially rescued the CCl4 injury-mediated fibrosis." (PMID 36293428, 2022). "Macrophages may contribute to fibrosis by producing large amounts of the profibrotic cytokines MIF and ECM1 to promote liver fibrosis in the CE lesion microenvironment." (PMID 36569953, 2022). "Also, ECM-1 expression decreases in patients with liver fibrosis and inversely correlates with severity of fibrosis, but little is known about the regulation of the immune system by ECM-1 in CLD." (PMID 33262757, 2020). "Meanwhile, ECM1, TRIB1, and CYP2C19 were downregulated, implicating impaired liver fibrosis regulation, carcinogen metabolism, and potential disruption of key signaling pathways." (PMID 41216224, 2025). "In different animal models of experimental liver fibrosis and in patients with chronic liver diseases (CLD), ECM1 expression decreased along with disease severity." (PMID 31718044, 2019).
liver fibrosis (continued). "ECM1 gene polymorphism in rs3834087 and rs3754217 loci is associated with a reduced risk of chronic HBV infection but not with liver fibrosis development and the occurrence of HCC." (PMID 36299684, 2022). "Depletion of ECM-1 severely affected liver architecture in mice, promoting liver fibrosis development, but without significant inflammation or hepatocyte damage." (PMID 33262757, 2020).
gastric cancer (12 papers, 2014 to 2026). A primary or metastatic malignant neoplasm involving the stomach. "ECM1 promotes tumor metastasis through epithelial–mesenchymal transition (EMT) progression, L Gan demonstrated ECM1 induced SOX2 expression via direct interaction with integrin β4 (ITGB4) in gastric cancer and thus altering gene expression of EMT factors." (PMID 31335317, 2019). "Compared to the non-cancerous counterparts, both mRNA and protein expression of ECM1 were elevated in gastric cancer tissue." (PMID 24779890, 2014). "Would this provide a clue of the prediction of ECM1 in carcinogenesis and metastasis of gastric cancer?" (PMID 24779890, 2014). "ECM1 protein expression was detected in 70.1% (54/77) of gastric cancer specimen, significantly higher than that in the corresponding counterparts (P <0.01)." (PMID 24779890, 2014). "ECM1 expression is aberrant elevated in tumor specimen and is closely related to the tumorigenic and metastatic potential of human gastric cancer." (PMID 24779890, 2014). "In addition, ECM1 promotes gastric cancer metastasis by the activation of FAK (Focal adhesion kinase)." (PMID 35784388, 2022). "ECM1 is upregulated in a variety of malignant epithelial tumors, including invasive breast ductal carcinoma, colorectal cancer, esophageal squamous carcinoma and gastric cancer, and functions as a oncogene in tumor development and prognosis." (PMID 31335317, 2019). "In the present work, we aimed to evaluate the role of ECM1 in gastric cancer and examined whether aberrant expression of ECM1 increased the tumorigenic and metastatic potential of human gastric cancer." (PMID 24779890, 2014). "In the present study, that ECM1 over-expression was positively correlated with increasing number of lymph microvessels in tumor specimen suggest the potential value of this protein in predicting lymphatic metastasis of gastric cancer." (PMID 24779890, 2014). "Therefore, we have attempted to determine the relationship between ECM1 expression, LMVD, and the clinicopathological parameters in gastric cancer patients to further discuss the clinical significance of ECM1 in carcinogenesis and lymphatic metastasis of human gastric cancer." (PMID 24779890, 2014). "Since ECM1 plays a vital role in the promotion for endothelial cells proliferation and lymphangiogenesis, we presumed that the protein might involve in lymphangiogenesis participating in the metastatic progression of gastric cancer." (PMID 24779890, 2014). "Extracellular matrix protein 1 (ECM1) mediates the activation of the FAK/SOX/HIF-1α axis by directly interacting with integrin β4 to increase metastasis and aerobic glycolysis in gastric cancer cells." (PMID 36407100, 2022). "A positive correlation was further established between ECM1 expression and LMVD in gastric cancer tissue (Spearman’s R = 0.407, P = 0.001)." (PMID 24779890, 2014). "Moreover, the role of ECM1 in the activation of Src by FAK has been identified in ovarian and gastric cancers." (PMID 35784388, 2022). "The mRNA and protein expression of ECM1 in gastric cancer specimen and the noncancerous counterparts from 77 patients were detected by real-time PCR and immunohistochemistry staining." (PMID 24779890, 2014). "In addition, FALEC expression was significantly increased in gastric cancer tissue samples, and after FALEC expression was silenced, the migration and invasion abilities of gastric cancer cells were inhibited due to decreased ECM1 expression in the cell line." (PMID 36139386, 2022). "However, whether ECM1 correlates to carcinogenesis and metastasis of gastric cancer has not yet been clarified." (PMID 24779890, 2014).